PLK3 (polo like kinase 3)
Diseases named in the same sentence as PLK3 in open-access papers (continued):
Sharing a sentence is not in itself a finding about the gene and the disease.
tumor (44 papers, 2004 to 2025). "In TCGAc databases, an association between PLK3 expression and T-cell immunity was found in the form of positive regulation of T-cell tolerance induction, T-cell-mediated immune response to tumor cells, and T-cell cytokine production." (PMID 39866232, 2025). "In aging mice, for example, Plk3 deficiency (in Plk3-KO mice) appears to accelerate tumor development and results in more pronounced angiogenesis and larger tumor size, indicating a tumor-suppressing function." (PMID 38630692, 2024). "PLK2 and PLK3 have been proposed to act as tumor suppressor proteins, and the loss of PLK2 was identified as a common change found in colorectal carcinomas, lending support to PLK2 being identified as a tumor suppressor." (PMID 35053604, 2022). "Supportive for this conception is the apparently more frequent development of spontaneous tumors in aged Plk3-deficient mice although the correlation between PLK3-deficiency and higher tumor incidence is questioned." (PMID 34065956, 2021). "Summarized, whereas PLK2 and PLK3 are considered to be tumor suppressors, PLK1 and PLK4 are associated with carcinogenesis and are often overexpressed in tumor cells." (PMID 33053667, 2020). "The association of Plk3 with tumor angiogenesis was discovered in a recent genetic study demonstrating that PLK3 null mice display an increased tumor incidence." (PMID 23210979, 2012). "We observed a decrease in neutrophil migration in PLK3-deficient tumor CM and an increase in neutrophil migration in CM from PLK3-overexpressing cells, indicating that PLK3 may promote neutrophil migration in the GBM microenvironment." (PMID 39866232, 2025). "While one study showed a non-tumorigenic phenotype in Plk3 deficient mice, another study reported that mice deficient in Plk3 develop highly vascularized tumors in multiple organs suggesting a tumor-suppressing activity in particular via HIF driven angiogenesis." (PMID 26942179, 2016). "Overall, these results demonstrate that PLK3 promotes GBM growth, and silencing the PLK3 gene strongly reduces viability, migration, and tumor-forming potential." (PMID 39866232, 2025). "Tumor development in the p48-cre;KrasLSLG12D;Plk3−/− mice was accompanied by an increase in Ki-67 staining and a decrease in apoptosis, as indicated by levels of caspase-3 activation." (PMID 38605037, 2024). "Polo-like kinase 3 (Plk3) has a tumor suppressive role through the induction of apoptosis, however, the mechanism underlying its activation is unclear." (PMID 38605037, 2024). "Given that the two closely related polo-like kinases, Plk2 and Plk3, are proposed to play tumor suppressor roles, the Plk1-specific inhibitory activity is an important property of Allopole-A." (PMID 37603740, 2023). "This points to an essential role of PLK3 as a mediator of tumor angiogenesis, which is a prerequisite for tumor growth." (PMID 34065956, 2021). "PLK3 has been found to be a critical player in cellular hypoxic responses, which contribute to tumorigenesis and tumor progression." (PMID 34065956, 2021). "Polo-like kinase 3 (Plk3) is a serine/threonine protein kinase of the Polo-like kinase family, which is critical for tumor suppression and stress responses (Barr, Sillje & Nigg, 2004)." (PMID 32140303, 2020). "In contrast genes involved in development and differentiation (Arid5b, Inmt, Grem2, Gdap10), cell metabolism (Alas1, Gsta1, Thrsp, Fdft1, Elovl6), tumor growth (SerpinA4, Cish, Rpl36), and cell cycle control (PLK3, Myc, HNF6/Onecut1) were downregulated." (PMID 33004985, 2020). "Polo-like kinase 3 (PLK3) has been documented as a tumor suppressor in several types of malignancies." (PMID 31655629, 2019).
tumor (continued). "In this study, HK2 expression level was found to be decreased under condition of PLK3 overexpression, while silencing PLK3 increased HK2 expression in tumor cells." (PMID 31655629, 2019). "As expected, PLK3 overexpression inhibited tumor growth and reduced tumor weight in the xenograft mouse model, whereas PLK3 knockdown had the opposite effects." (PMID 31655629, 2019). "After si-HK2 treatment, the increased glucose uptake and lactate production induced by PLK3 silencing were dramatically abolished in tumor cells." (PMID 31655629, 2019). "Assessing pre-treatment tumor samples, 54 patients (73%) presented with increased PLK3 expression, 33 (44.6%) with increased pT273 Caspase 8 levels, and 47 (63.5%) with high p16INK4a detection." (PMID 31475104, 2019). "Herein, we found that PLK3 was lowly expressed in 62.1% of tumor samples examined, suggesting that alteration of PLK3 level is a frequent event in human CRC." (PMID 31655629, 2019). "Plk3 is downregulated in various types of tumor cells and inhibits tumor cell proliferation and tumorigenesis." (PMID 30275866, 2018). "In contrast, the RNA expression levels of the two most closely related PLK family members, PLK2 and PLK3, were both lower in the tumor specimens (0.66 and 0.48-fold, respectively)." (PMID 29228663, 2017). "PLK3 is also involved in regulating a variety of molecular and cellular events, including DNA replication, DNA damage responses, cell cycle control and tumor angiogenesis." (PMID 27398719, 2016). "While the role of Plk1, the prototype member of the Plk family as a diagnostic marker and molecular target, has been extensively analyzed in a multitude of malignancies, the role of Plk3 seems to differ in various tumor entities." (PMID 27462786, 2016). "We have previously shown that elevated levels of HPV-16 viral DNA load and surrogate marker p16INK4a expression predict for improved local tumor control and OS in the patients cohort analyzed for Plk3 and pT273 caspase-8 levels in the present study." (PMID 27462786, 2016). "In the present study, we showed that high expression of Plk3 correlated with increased local tumor control and a long-term survival benefit in a cohort of 95 patients treated homogeneously by concomitant CRT." (PMID 27462786, 2016). "Since both Plk2 and Plk3 are required for promoting cell survival and they exhibit properties similar to tumor suppressors, specific inhibition of Plk1, but not Plk2 or Plk3, would be important for selectively killing cancer cells, but not normal cells." (PMID 26500787, 2015). "This study was prompted by genetic evidence showing the involvement of Plk3 in tumor angiogenesis and HIF-1α regulation." (PMID 23210979, 2012). "Given its documented roles in suppressing cell proliferation in vitro and tumor development in vivo, Plk3 represents an attractive target for the development of anti-cancer compounds." (PMID 23210979, 2012). "For example, the expression of Plk3 is down-regulated in several human cancers and Plk3 is therefore considered as a tumor-suppressor gene." (PMID 19161615, 2009). "In borderline tumours, there was considerable PLK3 positivity in two out of 13 cases (13.4%), although all cases showed scattered focal PLK3-positive cells." (PMID 14970859, 2004). "In the stroma of normal ovaries as well as in tumour stroma single inflammatory cells showing strong PLK3 expression were occasionally observed." (PMID 14970859, 2004). "The role of PLK3 in carcinogenesis depends on tumor type 82." (PMID 38169509, 2024). "Similarly, PLK3 was defined as a tumor suppressor, and under hypoxic conditions, functions as a negative regulator of HIF-1α." (PMID 35053604, 2022).
tumor (continued). "However, there was a high variability of Plk2 and Plk3 in both patient samples and cell lines and thus, more data on Plk2 and Plk3 expression in tumor cells relative to normal cells need to be gathered." (PMID 32060361, 2020). "Moreover, our previous investigation suggested that PLK2 promoted tumor growth and restrained cells apoptosis, while PLK3 seemed to have tumor-suppressive feature in CRC." (PMID 31655629, 2019). "To study the effects of PLK3 in vivo, we subcutaneously injected nude mice with tumor cells." (PMID 31655629, 2019). "Notably, there are controversial reports on the prognostic impact of PLK3 in different tumor entities." (PMID 31475104, 2019). "In line with these latter findings, we indicate a high expression of PLK3 to significantly correlate with improved distant tumor control and long-term survival in a CSCC cohort treated with definitive CRT plus BT, supporting its proposed tumor suppressor activity." (PMID 31475104, 2019). "To determine whether cell proliferation mediated by PLK3 reflects a change in glucose metabolism, we first examined lactate production and glucose uptake, two primary indicators of the Warburg effect in tumor cells." (PMID 31655629, 2019). "In vivo experiments also supported a tumor-suppressive function of PLK3 in CRC." (PMID 31655629, 2019). "Moreover, a remarkable correlation between PLK3 expression and tumor size, lymphatic metastasis and TNM stage was found." (PMID 31655629, 2019). "However, another Plk3-KO mouse generated by removal of exons 1–8 did show increased tumor formation in mice of advanced age." (PMID 26949938, 2016). "On the basis of our microarray data, apoptosis related tumor suppressors PLK3 and DDIT3 were upregulated after HOXA-AS2 inhibition, which elucidated that these two genes may also be key downstream mediators of HOXA-AS2." (PMID 26384350, 2015). "Both Plk2 and Plk3 are proposed to function as tumor suppressors." (PMID 26500787, 2015). "Moreover, we have observed that expression of Plk3 mRNA and protein is significantly deregulated in human melanoma cell lines and tumor tissues." (PMID 23210979, 2012). "Given the success of targeting protein kinases and tumor angiogenesis in anti-cancer therapies, Plk3 could be a potential molecular target for the development of novel and effective therapeutic agents for cancer treatment." (PMID 23210979, 2012). "In fact, Plk3 has been generally regarded as having a tumor-suppressing function." (PMID 23210979, 2012). "Moreover, CD4+ and CD8+ T-cells decreased in the Plk3-overexpressing tumor model." (PMID 39866232, 2025). "Based on these data, we hypothesized that Plk3 is a potential tumor suppressor." (PMID 38605037, 2024). "Notably, in this tumor entity for both PLK3 and pT273 caspase-8 signals a significant positive correlation to the extent of HPV infection was evident with quantitative HPV viral load and p16INK4a expression to further correlate to local control as well as patients overall survival." (PMID 31475104, 2019). "Furthermore, a significant association was observed between the PLK3 negative group and positive group in tumor size (P = 0.008), lymphatic metastasis (P = 0.027) and TNM stage (P = 0.019)." (PMID 31655629, 2019). "Interestingly, there are early reports showing that other Polo like family members might also play as tumor suppressors such as Plk3 or Plk510,42." (PMID 30069007, 2018). "In that context, we here demonstrate a highly significant correlation between Plk3 and pT273 caspase-8 detection and thus phosphorylation of caspase 8 may represent a mechanism by which different levels of Plk3 expression in tumor cells may stimulate the extrinsic apoptotic machinery." (PMID 27462786, 2016). "Under conditions of PLK3 overexpression, expression levels of HK2 decrease, while silencing PLK3 increases the expression of HK2 in tumor cells." (PMID 34217310, 2021).
tumor (continued). "In contrast, since PLK2 (also known as SNK) and PLK3 (also known as FNK or PRK) are tumor suppressors, development of a PLK1 inhibitor with isoform selectivity is very important." (PMID 33917995, 2021). "HOXA-AS2 inhibits the expression of P21, PLK3, and DDZT3 by binding to EZH2, promotes the proliferation of and inhibites the apoptosis of tumor cells." (PMID 32760226, 2020). "These include hypoxia-induced Polo-like kinase 3 (PLK3) engaged in the regulation of chaperone-mediated autophagy and pro-inflammatory chemokine IL-8 that promotes tumor immune escape." (PMID 32413951, 2020). "Our findings further indicate a prominent local effect of Plk3 expression and pT273 caspase 8 phosphorylation in response to RCT as exemplified by a significant impact on local tumor control." (PMID 27462786, 2016). "Plk3 can also phosphorylate and stabilize PTEN phosphatase, a known regulator of HIF-1α and tumor angiogenesis." (PMID 23327547, 2013). "In this review, we will discuss significance of Plk3 in HIF-1α regulation, tumor angiogenesis, and its potential as a therapeutic target for cancer treatment." (PMID 23210979, 2012). "Plk3 has also recently been found to phosphorylate and stabilize PTEN phosphatase, a known regulator of HIF-1α and tumor angiogenesis." (PMID 23210979, 2012). "Supporting this, PLK3 knock-out murine embryonic fibroblasts (MEFs) display significantly enhanced expression of HIF-1α and tumor angiogenesis in response to hypoxia." (PMID 23210979, 2012). "Moreover, we analyzed scRNA-seq data from 44 fragments of tumor tissue (GSE182109), and found PLK3 was highly expressed in MES cells, which was consistent with the analysis in pathology subtypes of GBM." (PMID 39866232, 2025). "Therefore drugs targeting this pocket address also other kinase domains affecting, among others, the tumor suppressor functions of PLK2 and in particular of PLK3 leading to adverse side effects." (PMID 34065956, 2021). "In conclusion, the present study demonstrates that PLK3 is frequently downregulated in tumor tissues compared to normal tissues." (PMID 31655629, 2019). "In these cases, the negative expression of PLK3 was detected in 72 (62.1%) of the tumor tissues, whereas 49 (42.2%) of the adjacent normal specimens showed a negative signal." (PMID 31655629, 2019). "Mouse genetic studies have yielded valuable information about Plk3's role in suppressing tumor angiogenesis through negative regulation of the PI3K signaling network and the HIF-1 activity." (PMID 23210979, 2012). "As mentioned for PLK1, nearly all PLK3-negative tumours expressed inhomogeneously small, albeit detectable amounts of cytoplasmatic PLK3 protein." (PMID 14970859, 2004). "The overexpression of either isoenzyme had an impact on patient prognosis with shortened survival time for patients with tumours positive for PLK1 (P=0.02) and PLK3 (P=0.02), but only PLK1 expression remained a prognostic factor in multivariate survival analysis (P=0.03)." (PMID 14970859, 2004). "For somatic copy number alterations, cases with high PLK3 expression not only demonstrated significant amplification peaks for PIK3C2B, PDGFRA, EGFR, and CDK4, which are defined as oncogenic drivers, but they also showed deletion peaks for tumor-suppressor genes, such as CDKN2A and CDKN2C." (PMID 39866232, 2025). "However, because Plk2 and Plk3 have functions akin to tumor suppression, it is desirable to inhibit Plk1 and not other Plks." (PMID 27874094, 2016). "There was a significant positive correlation for PLK3 (P=0.025) but not for PLK1 (P=0.125) expression with histopathological tumour grade, high-grade tumours being significantly more likely to express PLK3 than low-grade tumours." (PMID 14970859, 2004).
cancer (30 papers, 2007 to 2025). A tumor composed of atypical neoplastic, often pleomorphic cells that invade other tissues. "The reasons for these differential cancer type-related and possibly development-associated expression patterns of PLK3 remain elusive." (PMID 34065956, 2021). "It is also noteworthy to point out that the PLK3 gene is located at chromosome 1p34 where a high frequency of loss of heterozygosity occurs in many human cancers." (PMID 23210979, 2012). "In human PDACs, the simultaneous detection of loss of Plk3 expression and overexpression of Plk1 might disrupt the regulation of anoikis, subsequently fueling cancer progression and metastasis." (PMID 38605037, 2024). "Several studies demonstrated downregulated PLK3 expression may be linked with cancer development." (PMID 35139863, 2022). "Thus, the expression level of Plk3 may play a major role in Plk3's association with cancer development." (PMID 23210979, 2012). "PLK3, which played an important role in cell cycle progression and stress response, was identified as highly expressed in various carcinomas." (PMID 39866232, 2025). "Cyclin-dependent kinase 1A (CDKN1A), and Polo-like kinase 3 (PLK3) are cell cycle inhibitors, but CDKN1A overexpression has also been associated with increased cell migration and cancer stem cell promotion." (PMID 38674080, 2024). "PLK3 inhibits cancer cell growth and suppresses cellular glucose metabolism through the heat shock protein 90 (HSP90)/signal transducer and activator of transcription 3 (STAT3)/hexokinase 2 (HK2) pathways." (PMID 35487956, 2022). "Plk3 is a serine/threonine kinase that is known to be significantly involved in cell division as well as cancer formation and DNA damage." (PMID 35300109, 2022). "Expression of PLK3 is reduced in various cancers like lung, hepatocellular carcinoma, head and neck squamous cell carcinoma, anal squamous cell carcinoma as well as melanoma, liver, kidney, stomach, rectum, colon tumors, bladder, and uterus cancer." (PMID 34065956, 2021). "Supporting its role in cancer, PLK3 expression tends to be lower in many human malignancies, including those in the lung, head and neck, colon, kidney, liver, stomach, breast, and rectum." (PMID 33842469, 2021). "Similar to PLK1/2, PLK3 was involved in regulation of cell cycle progression, and it acted as a cancer suppressor in several types of malignancies." (PMID 34080290, 2021). "To elucidate the molecular mechanisms for PLK3-mediated glycometabolism, we analyzed differentially expressed genes for cancer cells using a human glucose metabolism PCR array." (PMID 31655629, 2019). "In this study, we found that low expression of PLK3 in CRC tissues was correlated with worse prognosis of patients and PLK3 inhibited cancer cells growth." (PMID 31655629, 2019). "We also identified three biological pathways including glycolysis, cell cycle checkpoint II and plk3 pathways in which most genes are systematically up-regulated in many types of cancer." (PMID 17989776, 2007). "Previous reports have suggested that PLK3 is distinctively expressed in different carcinomas." (PMID 39866232, 2025). "Altered checkpoint response in a cell-division transition may impact cell proliferation or apoptosis, providing a potential mechanism for Plk3 to modulate cancer development." (PMID 38605037, 2024). "The lower levels of PLK3 mRNA in cancer cells appear to be a result of reduced mRNA transcription." (PMID 23210979, 2012). "However, the function of PLK2 and PLK3 remains unclear, in cancer cells PLK2 and PLK3 exist as important mediators of stress phenotypes in response to DNA damage or oxidative stress." (PMID 23056340, 2012).